PTH (parathyroid hormone)
Diseases named in the same sentence as PTH in open-access papers (continued):
Sharing a sentence is not in itself a finding about the gene and the disease.
Hypercalcemia (continued). "Although the pathogenesis of gallstones in PHPT remains unclear, several factors including hypercalcemia, elevated PTH level, impaired contractility of the gallbladder and changes in bile composition may be implicated as the cause of cholelithiasis in PHPT." (PMID 29301445, 2018). "Laboratory analysis showed a hypercalcemia and plasma PTH of 398 pg/ml." (PMID 30317121, 2018). "Two months later, she was admitted to our unit for dehydration and hypercalcemia (3.64 mmol/L) with normal 25-OH vitamin D (113.1 nmol/L) and PTH (15 ng/L) levels and high 1,25-dihydroxyvitamin D levels (336 pmol/L), suggesting ectopic 25-hydroxyvitamin D3 1-alpha-hydroxylase activity." (PMID 30290590, 2018). "Laboratory findings (other than hypercalcemia) inpatients with symptomatic exogenous VDT related to overdosing of vitamin D or 25(OH)D show suppressed PTH (intact), 25(OH)D concentration>150 ng/ml (>375 nmol/l), and normal or increased values of 1,25(OH)2D concentration." (PMID 30294301, 2018). "Parathyroidectomy is indicated in refractory hyperparathyroidism when medical treatments and so the parathyroid hormone levels cannot be lowered to acceptable values without causing significant hyperphosphatemia or hypercalcemia." (PMID 30123263, 2018). "Hypercalcemia produced by parathyroid hormone also suppresses EAE." (PMID 28056806, 2017). "However, hypercalcemia and hyperphosphatemia are less frequent than in the 1980s because the serum PTH target has increased, from a normal value to two to nine times the upper limit of the assay, leading to reduce the VDRAs dosage." (PMID 28346348, 2017). "It accounts for 1% of PHPT cases and has symptoms commonly referred to as "bones, stones, abdominal moans, and psychic groans," attributable to hypercalcemia, elevated parathyroid hormone (PTH), nephrolithiasis, cognitive dysfunction, insomnia, fatigue, and bone demineralization." (PMID 29900020, 2017). "In this case, an osteolytic lesion and a PTH-dependent mechanism of hypercalcemia were excluded." (PMID 28977163, 2017). "In summary, we have established a mouse model for FHH2 and have shown the in vivo efficacy of cinacalcet in reducing plasma calcium and PTH concentrations, thereby illustrating the potential utility of this CaSR allosteric modulator for the treatment of hypercalcemia in patients with FHH2." (PMID 29046478, 2017). "One female patient who exhibited mild hypercalcemia, low PTH (8.6 pg/mL), normal 25OHD, and hypocalciuria was found to carry a de novo heterozygote mutation of the CaSR gene (p.994delK (C.2981del AGA) and was diagnosed as a case of familial hypocalciuric hypercalcemia (FHH)." (PMID 28443817, 2017). "Parathyroid hormone (PTH) release is often elevated, and severe hypercalcemia develops." (PMID 28157158, 2017). "Whether the chloride/phosphate ratio combined with alkaline phosphatase as a valuable predictive marker for PTH-independent hypercalcemia, further study is urged to for certification." (PMID 28687737, 2017). "Primary Hyperparathyroidism (PHPT) is characterized by hypercalcemia associated with elevated or non-suppressed serum parathyroid hormone (PTH) levels." (PMID 28600574, 2017). "However, hypercalcemia and raised PTH levels (169 pg/ml; normal value, 10 to 70 pg/ml) suggested a diagnosis of hyperparathyroidism." (PMID 29183364, 2017). "VDRAs are very efficient in decreasing serum PTH level, but could lead to adynamic bone disease and risks for toxicity and hypercalcemia, as reported initially when the target serum PTH value was lower." (PMID 28346348, 2017). "It is characterized by hypercalcemia and elevated levels of PTH." (PMID 27525132, 2016). "A low PTH (i.e. < 100 ng/L) in combination with hypercalcemia also prompted consideration of adynamic, or low-turnover, bone disease although this entity too did not fit with the prior chronically elevated PTH levels and the acuity of the calcium and PTH changes." (PMID 27683096, 2016).
Hypercalcemia (continued). "After withdrawal of the vitamin D analogue and initiation of daily hemodialysis, there was rapid dissolution of her tumoral calcium deposits with the abrupt onset of parathyroid hormone (PTH)-independent transient hypercalcemia that resolved once the soft tissue deposits disappeared." (PMID 27683096, 2016). "Double global CaSR knockout mice are used because deletion of the CaSR gene alone results in early death from the toxic effects of unregulated release of parathyroid hormone (PTH) from parathyroid chief cells as well as from the pathological effects of the consequent hypercalcemia." (PMID 27458380, 2016). "Resorption of soft tissue calcific deposits may result in transient parathyroid hormone (PTH)-independent hypercalcemia." (PMID 27683096, 2016). "She had been treated for 14 years, with an average dose of elemental phosphorus of 45.9 mg/kg per day (range 38–80 mg/kg per day) and alfacalcidol 34.2 ng/kg per day (range 22–49.6 ng/kg per day) the last 7 years before the development of permanently elevated PTH combined with hypercalcemia." (PMID 26543054, 2016). "A 25-year-old female presented with hypercalcemia and an inappropriately normal PTH." (PMID 27957351, 2016). "We also did not consider management of pre- or posttransplant hyperparathyroidism during our audit that may have impact on prevalence of hypercalcaemia as well as PTH levels." (PMID 27493801, 2016). "Hypercalcemia secondary to the secretion of parathyroid hormone (PTH) plays a major role in the pathogenesis, but other mechanisms may be involved." (PMID 27774509, 2016). "In all patients with hypercalcemia, the PTH level should be suppressed." (PMID 27335606, 2016). "Symptoms depended on the length and severity of PTH levels and hypercalcemia." (PMID 28003924, 2016). "Laboratory examinations revealed hypercalcemia and suppressed parathyroid hormone levels." (PMID 25878906, 2015). "Sixty-one patients had elevated calcium levels and/or a known history of PHP, while in 296 patients no PTH level was available; they either had a known non-PTH mediated cause, or the hypercalcemia was transient and was not evaluated further." (PMID 26239247, 2015). "A recent meta-analysis of 21 nonrandomized studies including a total of 411 kidney transplant recipients with hypercalcemic hyperparathyroidism showed that cinacalcet corrects hypercalcemia and lowers parathyroid hormone (PTH) levels also in kidney transplant patients." (PMID 25861621, 2015). "It is possible that hypercalcemia suppresses PTH secretion, and that its feedback inhibition may provide a beneficial physiological balance in hyperparathyroidism." (PMID 26107510, 2015). "Hypercalcemia is rarely encountered in patients with acromegaly and might be PTH-dependent or 1,25(OH)2D-dependent." (PMID 26082755, 2015). "Our case report suggests that hypercalcaemia may result from the overproduction of PTHrP in patients with renal injury and adequately suppressed PTH." (PMID 26019888, 2015). "It is characterized by hypercalcemia, increased levels of PTH and slight hypophosphatemia." (PMID 25241609, 2014). "Given one of the proposed etiologic mechanisms of injury and vascular calcification of calciphylaxis is elevated serum PTH, hypercalcemia, and hyperphosphatemia, it made sense to us that lanthanum improved the clinical status by directly affecting these laboratory values." (PMID 25254144, 2014). "However, PTH was injected only for 6 days for the treatment of stroke, so the hypercalcemia effect should be minimal in this relatively short period of PTH administration." (PMID 24503654, 2014). "Our primary hypothesis is that since calciphylaxis represents the ultimate sequelae of metastatic vascular calcification predominantly involving hyperphosphatemia, elevated serum PTH, and hypercalcemia, lanthanum carbonate will be efficacious in its treatment." (PMID 25254144, 2014).
Hypercalcemia (continued). "Since the proposed etiologic mechanism of injury and vascular calcification of calciphylaxis is predominantly hyperphosphatemia, elevated serum PTH, and hypercalcemia, lanthanum carbonate would be an ideal pharmacologic agent to utilize in this extremely enigmatic disease." (PMID 25254144, 2014). "The most common PTH-independent type of hypercalcemia is malignancy related." (PMID 24716007, 2014). "During a 4 years follow-up period hypercalcemia, hypercalciuria and normal levels of PTH persisted." (PMID 25292184, 2014). "Hyperparathyroidism was diagnosed by laboratory tests as hypercalcemia and increased levels of PTH." (PMID 25241609, 2014). "Previous data suggest that calcitriol may have greater parathyroid hormone (PTH)-lowering effects and a greater risk of hypercalcemia than nutritional compounds." (PMID 24930018, 2014). "Four mechanisms of hypercalcemia in malignancy have been described: local osteolysis, parathyroid hormone related-protein (PTHrP) mediated, 1,25-dihydroxyvitamin D (1,25(OH)2D3, calcitriol) secretion, and ectopic parathyroid hormone (PTH)." (PMID 24721620, 2014). "If PTH is injected only once a day, fluctuations in calcium levels may occur resulting in hypercalcemia in the hours following an injection." (PMID 25101193, 2014). "After surgical treatment, hypercalcemia was normalized and PTH-rp became undetectable." (PMID 24200238, 2013). "Patients may also experience reversible hypercalcaemia as a result of increased parathyroid hormone concentration." (PMID 23761028, 2013). "OPG has been shown to inhibit hypercalcemia and bone resorption induced by administration of PTH." (PMID 22997530, 2012). "Interestingly, deletion of PTH in CaR−/− mice also corrects the hypercalcemia, and the mice develop hyperphosphatemia and undetectable serum PTH with enlarged parathyroid glands." (PMID 21966280, 2011). "There is a possibility that hypercalcemia and/or a chronic exposure to high PTH levels might affect the arterial tone." (PMID 21403888, 2011). "Hypercalcemia as the main clinical issue can almost always be sufficiently controlled as well as hypophosphatemia, PTH levels may be lowered, and cognitive as well as HRQOL parameters improve with the treatment." (PMID 21461394, 2011). "Similarly, immunization with anti-PTH antibodies was effective in controlling hypercalcemia for more than 72 months in patients with unresectable parathyroid carcinoma in Phase III clinical trials." (PMID 21625386, 2011). "We also think that DNA sequencing is minimally invasive, is becoming more affordable, can lead to accurate diagnosis, and should therefore be carried out in members of PTH-related families with hypercalcemia and hypercalcemia patients with overlapping fraction of excretion of calcium (0.01 to 0.02)." (PMID 21034470, 2010). "The patients with malignancy-associated hypercalcemia had a biochemical profile similar to hyperparathyroidism, but in many cases the parathyroid hormone (PTH) levels were not elevated." (PMID 21731261, 2010). "Similarly to PTH, PTH-rP interacts with the PTH/PTH-rP receptor that mediates the renal tubular reabsorption of calcium and stimulates osteoclastic bone resorption resulting in hypercalcemia." (PMID 19878543, 2009). "In addition, it has also been shown that Amifostine can normalize hypercalcemia through its PTH-independent inhibitory effect on TRCa." (PMID 19758462, 2009). "Thus, an important criterion essential to make a differential diagnosis is the research of hyperparathyroidism and hypercalcemia, alteration in calcium-phosphorous balance and increase of parathyroid hormone (PTH) in blood chemistry." (PMID 19088886, 2008). "Preoperative serum calcium and intact-parathyroid hormone levels are the most useful diagnostic parameters that allow differentiating primary hyperparathyroidism from non-parathyroid-dependent hypercalcemia." (PMID 18291038, 2008).
Hypercalcemia (continued). "Hypercalcemia can occur in granuloma forming disorders such as sarcoidosis, because of extra renal production of 1,25-dihydroxyvitamin D. PTH release is inhibited by hypercalcemia and high levels of calcitriol, which explains the suppressed PTH level in sarcoidosis." (PMID 18652699, 2008). "Parathyroid adenoma with hypercalcemia exhibiting normal parathyroid hormone level is rare." (PMID 18291038, 2008). "This case highlights the importance of multidisciplinary team input in managing uncommon causes such as sarcoidosis as a differential diagnosis for PTH-independent hypercalcemia, as it has a multisystemic and nonspecific presentation, with biopsy and radiographic findings as key to diagnosis." (PMID 39906901, 2025). "Patients may present with hypercalcemia, suppressed PTH, hypercalciuria, and renal stones." (PMID 40765620, 2025). "However, the detection of elevated intact parathyroid hormone (PTH) confirmed that the hypercalcemia was not solely due to prolonged immobilization associated with GBS but rather due to previously latent PHPT becoming clinically apparent." (PMID 40109792, 2025). "Finally, hypocalcemia after sepsis stimulates the release of PTH to restore normal calcium levels, but persistent sepsis combined with multiple organ failure can lead to sustained parathyroid hormone release, resulting in hypercalcemia and even life-threatening complications." (PMID 40595809, 2025). "This patient also showed signs of hyperparathyroidism (elevated intact parathyroid hormone), resistant to bisphosphonates, further clouding her diagnosis of mycobacterial endocarditis, as her altered mental status was originally explained by hypercalcemia instead of septic embolic strokes." (PMID 41246773, 2025). "GIST-related hypercalcemia is rare and may result from tumor secretion of PTHrP or 1-alpha-hydroxylase–mediated overproduction of 1,25-dihydroxyvitamin D, often presenting with suppressed PTH levels." (PMID 41479802, 2025). "This discrepancy may stem from long-term vascular remodeling caused by chronic hypercalcemia and elevated PTH levels, which might not fully reverse after surgery, especially given the prolonged time to intervention (mean 879 [1219] days)." (PMID 41269693, 2025). "Interestingly, there is a report of a patient with CYP24A1-associated hypercalcemia and normal (non-suppressed PTH), who had an enlarged parathyroid gland removed with persistent hypercalcemia and then suppression of PTH." (PMID 40765620, 2025). "Chronic elevation of PTH, even in the absence of hypercalcemia, may increase the risk of cortical bone loss and osteoporosis, as observed in normocalcemic primary hyperparathyroidism." (PMID 40707943, 2025). "The simultaneous elevation of FGF-23 and PTH may decrease serum phosphorus levels, thereby protecting against ectopic calcification and tissue damage by reducing the calcium-phosphate product in the presence of hypercalcemia." (PMID 41509939, 2025). "It has been speculated that estrogen acts as a regulator for PTH's effect on bone by inhibiting bone resorption, and that, during menopause, the state of estrogen insufficiency eliminates this regulation, enabling PTH to fully affect bone, resulting in hypercalcemia." (PMID 40177730, 2025). "Primary hyperparathyroidism (PHPT), a relatively common disorder characterized by hypercalcemia with raised or inappropriately normal serum parathyroid hormone (PTH) concentrations, may occur as part of a hereditary syndromic disorder or as a non-syndromic disease." (PMID 38038882, 2024). "Also, as FGF23 lowers PTH gene expression and secretion, inhibiting FGF23 may cause hyperparathyroidism, which can also lead to hypercalcemia and HC." (PMID 39687707, 2024).
Hypercalcemia (continued). "A possible hypothesis to justify this difference between the groups would be that the group with low PTH levels may have greater variation in calcium levels due to oral supplementation; therefore, transient hypercalcemia may increase the calcium–phosphorus product and promote vascular calcification." (PMID 38578437, 2024). "As denosumab is a frequently used drug in patients with advanced malignant diseases and rebound hypercalcemia with low PTH levels may raise the suspicion for skeletal metastases, awareness of this rebound effect may be for particular relevance in such settings." (PMID 39529981, 2024). "As denosumab is a frequently used drug in patients with advanced malignant diseases, and rebound hypercalcemia with low PTH levels may raise the suspicion for skeletal metastases, awareness of this rebound effect may be of particular relevance for further patient management in such settings." (PMID 39529981, 2024). "Hypercalcaemia with suppressed PTH suggested a non-parathyroid cause of hypercalcaemia." (PMID 39434928, 2024). "Of note, only 13 participants exhibited increased serum ionized calcium, and the majority of our cohort did not demonstrate overt hypercalcemia, which may have further weakened the association between PTH and reduced CYP24A1 activity." (PMID 38765596, 2024). "Indeed, a normal ionized calcium serum level in the setting of an increased serum PTH concentration may lead to a diagnosis of NHPT if hypercalcemia is unmasked after a calcium load together with an inadequate serum PTH level inhibition." (PMID 38497124, 2024). "In a recent study investigating the CaSR in cats with CKD with and without concurrent hypercalcemia, an association was found between 1/12 CaSR single nucleotide polymorphisms (SNPs) and PTH concentration, but not iCa concentration; however, calcitonin concentration was not measured." (PMID 38887540, 2024). "Regarding the digestive panel (including pancreatic insulin profile), several clusters should be specified: firstly, anorexia, nausea, and vomiting may be a consequence of PTH-dependent hypercalcemia, a gastro-duodenal ulcer or pancreatitis, or a connected complaint related to nephrolithiasis." (PMID 38928056, 2024). "Additionally, PTH was only assessed in patients with hypercalcemia." (PMID 38281931, 2024). "We speculate that the cause of his severe hypotension was vasodilation due to the transient release of parathyroid hormone from mechanical stimulation by anesthetic procedures, such as tracheal intubation, combined with hypercalcemia-induced severe dehydration." (PMID 39213244, 2024). "Hypercalcemia is a less frequently reported rebound phenomenon after denosumab discontinuation, that may pose a diagnostic challenge to physicians as a rare non-parathyroid hormone (PTH) dependent cause of hypercalcemia." (PMID 39529981, 2024). "In addition, the patient exhibited hypercalcemia and elevated levels of parathyroid hormone." (PMID 39183425, 2024). "Additionally, CaSR is involved in the intracellular degradation of PTH during hypercalcemia." (PMID 38920679, 2024). "Moreover, when sarcoidosis is suspected, hypercalcemia with low parathyroid hormone levels and normal or low 25-hydroxycalciferol levels may be favored." (PMID 39598118, 2024). "In addition, the demographic data of the patients, baseline creatine, calcium, phosphorus, and PTH levels at the time of hypercalcemia, parathyroid ultrasonography, parathyroid scintigraphy, creatinine, calcium, phosphorus, and PTH levels in the last controls, and survival status were evaluated." (PMID 37069889, 2023). "There are two principles for the treatment of hypercalcemia in clinical practice, namely using normal saline expansion and loop diuretics and second, using drugs such as calcitonin, diphosphate, cinacalcet, and denosumab to inhibit bone resorption and PTH secretion." (PMID 38019325, 2023).